GPX4 (glutathione peroxidase 4)
Diseases named in the same sentence as GPX4 in open-access papers (continued):
Sharing a sentence is not in itself a finding about the gene and the disease.
tumor (continued). "Increases in GPX4 in tumor cells have been shown to inhibit ferroptosis." (PMID 37371096, 2023). "Thus, GPX4 is considered an important inhibitor of ferroptosis, and ample compounds such as gallic acid, withaferin A, and oridonin were reported to induce ferroptosis in tumor cells through downregulation of GPX4 expression." (PMID 37408372, 2023). "We found that the costimulatory molecules TNFSF15 and TNFSF9 were overexpressed in the siGPX4 group, suggesting that GPX4 knockdown could inhibit tumor angiogenesis." (PMID 37649598, 2023). "Low GPX4 was also observed in tumor bearing RUNX1-IT1-silenced MDA-MB-231 cells." (PMID 37036576, 2023). "Moreover, we found that tumour growth was obviously attenuated by overexpression of circIDE, while the effects of circIDE were reversed by additional transduction of GPX4 overexpression lentiviral." (PMID 36989117, 2023). "Deficiency of GPX4 causes iron death of DTC cells in vitro and prevents tumour recurrence in vivo." (PMID 37483492, 2023). "At any rate, GPx4 does prevent ferroptosis, and this may inspire cytoprotective pharmacological strategies, but this may also have deleterious effects on tumor growth and anti-cancer therapy." (PMID 37373256, 2023). "Furthermore, in an in vivo study, 5-aminolevulinic acid, a natural amino acid, suppressed GPX4 and resulted in tumor shrinkage." (PMID 36576648, 2023). "GPX4-deficient T cells can rapidly accumulate membrane LPO and lead to ferroptosis, and therapeutic induction of ferroptosis in tumor cells by GPX4 inhibitors may have unnecessary effects on T cells." (PMID 37064872, 2023). "In addition, significant progress has been made in researching and developing tumor therapeutic drugs targeting GPX4 based on ferroptosis, especially in acquired drug resistance." (PMID 36675129, 2023). "Moreover, cisplatin lowers GSH levels in tumour cells, compromising GPX4 function and triggering ferroptosis in NSCLC cells." (PMID 38273826, 2023). "We also found that PD-L1 mRNA expression was significantly reduced in the siGPX4 group, suggesting that GPX4 knockdown could inhibit PD-L1 expression and prevent tumor immune escape." (PMID 37649598, 2023). "Furthermore, vorinostat repressed tumor growth and downregulated the expression of GPX4 and NRF2 in JAR cell‐bearing mice model." (PMID 36106577, 2023). "Relevant literature has shown that GPX4 can promote tumor migration and invasion." (PMID 37077773, 2023). "Combination therapy using GPX4 inhibitors and immunotherapy can further activate T cell infiltration in the tumor microenvironment (TME), and its clinical efficacy is significantly superior to that of monotherapy, indicating its potential as a novel precision medicine strategy in LAR-type TNBC." (PMID 38065948, 2023). "Similarly, in the naive tumour, GPX4 and anti-ferroptosis genes were upregulated in RMC compared to TAL cells." (PMID 37236926, 2023). "Studies have reported that ferroptosis inducers (such as RSL3, erastin, sorafenib, and sulfasalazine) can enhance the effectiveness of radiotherapy by inhibiting SLC7A11 or inactivating GPX4 in tumor models such as glioma, lung cancer, fibrosarcoma, melanoma, breast cancer, and cervical cancer." (PMID 38139836, 2023). "Therefore, exploring effective GPX4 regulation mechanisms is critical for tumor therapy based on ferroptosis." (PMID 38102129, 2023). "Additionally, we stained GPX4 and Ki-67 to detect the expression levels in the tumor tissues by immunohistochemical staining and obtained the corresponding trends, which were coincident with the experiments in vitro." (PMID 38102129, 2023). "They found that the expression of GPX4 decreased significantly during tumor relapse." (PMID 36185243, 2022). "The xenograft tumor model also showed that GPX4 knockdown markedly reduced tumor growth in mice." (PMID 35962333, 2022).
tumor (continued). "CASP8, CASP6, GSDME, NOD1, and GPX4 were significantly upregulated in tumor tissues compared to the normal tissues, whereas IL6, IL1B, NLRP3, and NLRC4 were downregulated, suggesting that pyroptosis-related genes play important roles in tumor progression and prognosis." (PMID 35559014, 2022). "Indeed, an overwhelming amount of literature data showed the great sensitivity of cancer cells across a wide range of tumor types to ferroptosis induction by xCT or GPx4 inhibition." (PMID 35804926, 2022). "Moreover, a positive correlation between SCD1/FADS2 and SCD1/GPX4 in OvCa tumor tissues was observed by regression analysis in TCGA-OV." (PMID 35547771, 2022). "Zn-Fu MNs also exhibited good GPX4 down-expression and lipid oxidation within tumor." (PMID 36168615, 2022). "All these data provide evidence that GPX4 could act as a tumor activator for the growth of EC, and that knockout of GPX4 enhances ferroptosis activity in vivo." (PMID 35962333, 2022). "The inhibition of GPX4 drastically suppressed the tumor volume." (PMID 35962333, 2022). "It is known that as a ferroptosis inducer, RSL3 inhibits tumor growth by targeting GPX4." (PMID 36618071, 2022). "Ferroptosis has become a hot research topic in tumor; the pathway network between iron metabolism, Fenton reaction, Xc-system, and GPX4 has been initially established; and other important related pathways (including transsulfur pathway) and ferroptosis-related drugs need to be further investigated." (PMID 35958626, 2022). "Additionally, GPX4 knockdown significantly suppresses tumor cell proliferation in vitro and in vivo." (PMID 35105963, 2022). "RAD21, BOP1, POLR2E, and PRKDC were mainly expressed in tumor cells, RIPK2 was mainly expressed in monocytes, MAP2K2 was mainly expressed in tumor cells and macrophages, NBN was mainly expressed in macrophages and monocytes, and GPX4 was mainly expressed in tumor cells and T cells." (PMID 36212155, 2022). "Depletion of GSH and inactivation of GPX4 synergistically lead to ferroptosis of tumor cells." (PMID 39070608, 2022). "However, In the xenograft model, the inhibition of GPX4 restrain tumor regrowth after discontinuation of 5-FU treatment." (PMID 36105219, 2022). "We treated human TC cells (K1, MDA-T68, MDA-T32, TPC1) with (1S,3R)-RSL3 (RSL3), a small-molecule inhibitor of GPX4 and examined the effects on ferroptosis, tumor cell survival and migration, spheroid formation, oxidative stress, DNA damage repair response, and mTOR signaling pathway in vitro." (PMID 36371529, 2022). "have reported that glutathione peroxidase 4 (Gpx4) could prevent Treg cells from lipid peroxidation and ferroptosis in regulating immune homeostasis and anti-tumor immunity." (PMID 36569832, 2022). "Moreover, the expression of GPX4 in the tumour tissue was confirmed to be downregulated by sh-GPX4 transfection and significantly reduced by tumour irradiation." (PMID 36050447, 2022). "The high expression of SLC1A5 could reduce oxidative stress damage under tumor hypermetabolism through increasing the expression of GPX4, which further accelerates cell proliferation and malignant progression." (PMID 36566214, 2022). "Moreover, a new type of agent based on arginine-rich manganese silicate nanobubbles (AMSNs) was reported to induce ferroptosis by depleting GSH efficiently and inactivating GPX4, which can obtain a significant tumor suppression result then." (PMID 36005616, 2022). "Furthermore, a remarkable remission in tumour growth was observed upon combining this approach in GPX4 knockout tumours." (PMID 35908258, 2022). "Targeted ablation of Gpx4 in Treg inhibited tumor growth and potentiated anti-tumor immunity." (PMID 35432318, 2022).
tumor (continued). "Under the surviving stress upon TKIs, elevated METTL7B in LUAD cells accelerated the scavenging of excessive ROS in tumor microenvironment by upregulating the protein levels and enzymatic activities of three antioxidant enzymes GPX4, SOD1 and HMOX1 by m6A modification in their mRNAs." (PMID 35144642, 2022). "Moreover, combined treatment with brequinar and sulfasalazine synergistically facilitates ferroptosis and efficiently abrogates tumor growth induced by cells with high expression of GPX4." (PMID 35882850, 2022). "Since tumor samples have low methylation in the GPX4 promoter region, low methylation and high histone acetylation may lead to the overexpression of GPX4 in tumor cells." (PMID 36157228, 2022). "In addition, we found that GPX4 can be used as a new transcriptional target of ELK1, and the tumor progression caused by the overexpression of ELK1 can be attenuated by downregulating the expression of GPX4." (PMID 35962333, 2022). "Moreover, Western blotting results suggested that knockdown of GOT1 expression similarly reduced GPX4 protein expression in tumor tissues." (PMID 36497150, 2022). "GPX4 is the cause of ferroptosis induced by lipid peroxidation signals; therefore, knocking down the expression of GPX4 is enough to induce ferroptosis, and GPX4 inhibitors may be potential candidates for tumor treatment." (PMID 36317423, 2022). "It is noteworthy that GPX4 may produce unnecessary targeting effects on CD8+T cells in the anti-tumor process, leading to adverse reactions." (PMID 35911967, 2022). "By inhibiting the key active site of GPX4 selenocysteine and systematically screening ferroptosis inducers, it may be possible to combat tumor chemotherapy resistance." (PMID 36317423, 2022). "Indeed, IHC staining also showed that COX2 was higher, while the ferroptosis proteins SLC7A11 and GPX4 were lower in the subcutaneous tumour specimens of the Huaier-treated group compared to those of the control group." (PMID 36248959, 2022). "Importantly, DHODH inhibitor brequinar selectively suppresses GPX4-low tumor growth by inducing ferroptosis, whereas combined treatment with brequinar and sulfasalazine synergistically induces ferroptosis and suppresses GPX4-high tumor growth." (PMID 35174081, 2022). "GPX4 remains an important target of microRNAs in tumor diseases." (PMID 36310600, 2022). "GPX4 uses GSH to improve the antioxidant activity of tumor cells, thereby suppressing ferroptosis." (PMID 35517862, 2022). "Whether knocking out the GPX4 gene or inhibiting its activity, it can eventually lead to a redox homeostasis imbalance that can have a fatal effect on normal or tumor cells." (PMID 36105219, 2022). "RSL-3 inhibited the activity of GPX4 in the antioxidant system to induce ferroptosis of tumor cells, which could rewire tumor metabolism and make tumor cells extremely sensitive to SDT-induced apoptosis." (PMID 36131565, 2022). "The tumor weight of shGPX4 group also decreased remarkably after GPX4 knockdown." (PMID 35962333, 2022). "MicroRNAs essentially regulated tumor ferroptosis via the antioxidant system, whether by regulating GPX4, FSP1, or GSH." (PMID 36310600, 2022). "To determine whether GPX4 inhibition affects tumor cell viability, we treated PTC cells with various concentrations of RSL3 and performed a cellular viability assay." (PMID 36371529, 2022). "In addition, patients with high AMPK and low GPX4 expression typically had lower pathological T and M grades as well as neoplasm histological grade and pathological stage." (PMID 36246395, 2022). "Furthermore, GPX4-deficient Treg lymphocytes can decrease the number of Treg lymphocytes in TME and the enhance the anti-tumor immune response, thereby repressing tumor growth." (PMID 35619718, 2022). "This is because NF2 knockout facilitates tumor cell metastasis, which GPX4 knockout inhibits." (PMID 35911967, 2022). "Studies have improved that tumor cells with drug resistance are more sensitive to GPX4." (PMID 36005616, 2022).
tumor (continued). "In addition, IHC and western blot assays were performed to determine the expression levels of SFRS9 and GPX4 in tumor tissues." (PMID 34336668, 2021). "Importantly, GPX4 inhibition using RSL3 with sorafenib therapy elicited a significant tumor regression in Gstz1−/− mouse models in vivo." (PMID 33931597, 2021). "To further test GPX4 dependence of tumor platinum sensitivity in vivo, we also genetically suppressed the expression of GPX4 by shGPX4 transfection and implanted GPX4 knockdown PC9‐BrM3 cells (BrM3‐shGPX4) into nude mice by subcutaneous and intracardiac injection, respectively." (PMID 34586745, 2021). "Additionally, GPX4 is necessary for tumor recurrence, indicating that eradicating drug-resistant cancer cells by targeting GPX4 to induce cellular ferroptosis is a promising clinical strategy." (PMID 35118067, 2021). "The data suggest that GPX4 inhibitors, should these become clinically viable, may enhance the anti-tumor activity of αESA." (PMID 33854057, 2021). "PANC1 cells with LONP1 interference were less sensitive to erastin than control cells, but GPX4 expression and the GSH content were increased; thus, LONP1 was concluded to induce a tumour suppressor effect by downregulating GPX4 expression and reducing the GSH content." (PMID 34503532, 2021). "GPX4 inhibition could render therapy-resistant tumor cells more sensitive to ferroptosis, but a variety of tumor cells can evade RSL3-induced ferroptosis." (PMID 34178977, 2021). "Thus, if the cellular content of GPX4 is high the tumor cells are drug-resistant and such drug-resistant tumor cells can be rendered drug sensitive by reducing intracellular GPX4 levels and enhancing accumulation of lipid peroxides." (PMID 33567774, 2021). "Besides, GPX4 is key factors involved in ferroptosis and lipid metabolism that regulate tumor metastasis." (PMID 35154262, 2021). "In addition, we found higher GPX4 expression in SFRS9 overexpressed tumor tissues and lower GPX4 expression in SFRS9 inhibited tumor tissues compared with their respective controls." (PMID 34336668, 2021). "In addition, after knockdown of BRD4 or under (+)-JQ1 (an inhibitor of the tumor-driver bromodomain protein BRD4), the expressions of ferroptosis-associated genes GPX4, SLC7A11, and SLC3A2 are downregulated." (PMID 34222241, 2021). "GPX4 plays an important role in the resistance of tumor cells by regulating ferroptosis." (PMID 32656078, 2020). "Data analysis shows that GPX4 is highly expressed in tumor tissues, compared with adjacent tissues." (PMID 33425217, 2020). "Although increased GPX4 expression promotes drug resistance in tumor therapy, the role of GPX4 in tumorigenesis remains unknown." (PMID 32596160, 2020). "To examine if GPX4 replenishment could rescue the tumor cells from ferroptosis, we ectopically expressed recombinant GPX4 (rGPX4) in LN229TAZ(4SA) cells." (PMID 33110073, 2020). "Furthermore, sh-GPX4 treatment reduced the growth rate of tumor in nude mice, and further strengthened the inhibitory effect of gefitinib on tumors." (PMID 33425751, 2020). "Our animal studies indicate that GPX4 may play a tumor suppressor-like role, whereas TMEM173 may have an oncogenic-like role in pancreatic tumorigenesis." (PMID 33311482, 2020). "Moreover, the intratumoral levels of Ubs and caspapse-3 were up-regulated whereas GPX4 was down-regulated after PdPT treatment in these xenograft tumor mouse models." (PMID 32596160, 2020). "And we found that HMGB1, GPX4 and p-p65 were expressed in the tumor tissues." (PMID 32514250, 2020). "Further studies have found that GPX4 plays an important role in tumor resistance." (PMID 32656078, 2020). "The upstream of GPX4 is characterized by lower DNA methylation sites and elevated H3K4me3 and H3K27ac levels, suggesting that enhanced expression of GPX4 in tumor tissues may result from epigenetic regulation." (PMID 33425217, 2020).
tumor (continued). "THBS1 upregulation together with the impaired migration of endothelial cells might be the mechanisms how GPx4 inhibits tumor angiogenesis." (PMID 29515790, 2018). "However, while GPX1 and GPX4 were more highly expressed in tumor tissue from the Czech and Irish cancer groups, respectively, TXNRD1 was not significantly different in any of our tested cohorts." (PMID 30469315, 2018). "It is thus not surprising that GPX4, ferroptosis and cancer are linked in several tumor entities including breast cancer, sarcomas and B cell lymphomas." (PMID 30534534, 2018). "Interventional enhancement of GPx4 levels might also increase tumor-infiltrating M1 macrophages as an adjuvant tool to enhance immune therapy responses." (PMID 29515790, 2018). "However, the exact mechanism of interplay of Gpx4 and specific tumor host microenvironment is still under investigation." (PMID 27023612, 2016). "Thus, while ferroptosis activation may be efficacious alone or in combination with other therapies in specific tumor contexts, cell culture systems greatly overestimate the potential anti-cancer effects of ferroptosis induction via the GPX4 axis." (PMID 41959261, 2026). "In addition, GPX4-deficient tumor cells secrete TAG and oxTAG into the extracellular space to induce dysfunction of antitumor CD8+ T cells, thereby coordinating an immunoinhibitory tumor microenvironment (TME)." (PMID 41259048, 2026). "In addition, it could suppress tumor growth in an orthotopic mouse model of GC by regulating the expression of GPX4 and NOCA4." (PMID 41526983, 2026). "Additionally, targeting GPX4 may represent a novel strategy to improve the anti-tumor effects of lapatinib." (PMID 40427734, 2025). "Interestingly, tumour burden and the high metabolic activity of the tumour cells in the latter study were shown to be dependent upon inhibition of ferroptosis through sustained expression of GPX4." (PMID 40853521, 2025). "Moreover, circular RNA circ0060467 acts as a molecular sponge for miR-6805, alleviating miRNA-mediated repression at the post-transcriptional level and increasing FSP1 and GPX4 mRNA abundance, thus ultimately enhancing their expression, inhibiting ferroptosis, and promoting tumor growth in HCC." (PMID 40862825, 2025). "Interestingly, CD8 + T cells are more prone to ferroptosis induced by GPX4 inhibition than tumor cells, suggesting that direct induction of ferroptosis within the TME may be less than ideal." (PMID 40285867, 2025). "By understanding the mechanism of ferroptosis, it is possible to overcome tumor resistance or synergy with conventional therapies to enhance therapeutic efficacy, such as chemotherapy; for example, the quinazolinyl‐arylurea derivative 7j can bind to active GPX4 to induce ferroptosis." (PMID 41438182, 2025). "Additionally, GPX4 expression correlated with tumor grade and cancer stage." (PMID 41142608, 2025). "An experimental analysis of a group of cancer cell lines with low and high GPX4 expression demonstrated that inhibiting DHODH could induce ferroptosis in tumor cells with low GPX4 expression while enhancing ferroptosis resistance in cancer cells with high GPX4 expression." (PMID 40740786, 2025). "Thus, inhibition of GPX4-targeted ferroptosis in tumor Tregs could be a direction to reprogram TME and treat cancer." (PMID 40855044, 2025). "Moreover, the level of GPX4 protein can be reduced by 150 mg/kg BSN in tumor tissues." (PMID 39846413, 2025). "TIPE2-deficient MDSCs resisted IKE-induced ferroptosis by up-regulating SLC7A11 and GPX4, and dissolved ferroptosis-induced immunosuppressive function by down-regulating lipid ROS whilst encouraging T cell proliferation and infiltration into tumor tissues to improve ferroptosis therapy." (PMID 39851538, 2025).